C2orf80 (chromosome 2 open reading frame 80)
Synonyms: LOC389073; GONDA1
Tractability: No criterion of Open Targets' tractability assessment is met for any kind of drug.
Gene: Protein-coding gene on chromosome 2 (208,165,343 to 208,190,245, reverse strand). Ensembl gene ENSG00000188674.
Subcellular location (Human Protein Atlas): Golgi apparatus
Genetic constraint (gnomAD): Loss-of-function variants: 19 observed, 21.39 expected, observed/expected ratio (o/e) 0.89, 90% interval 0.62 to 1.3. The upper end of that interval is the gene's LOEUF score, 1.3, which puts it in group 5 of 6, group 1 being the genes least tolerant of losing a copy. Missense variants: 170 observed, 190.09 expected, observed/expected ratio (o/e) 0.89, 90% interval 0.79 to 1.02. Synonymous variants: 63 observed, 65.6 expected, observed/expected ratio (o/e) 0.96, 90% interval 0.78 to 1.18.
Homologues: Orthologues: chimpanzee C2orf80 (98% identical), macaque C12H2orf80 (86% identical), pig C2orf80 (80% identical), guinea pig C2orf80 (77% identical), dog C2orf80 (76% identical), mouse D630023F18Rik (66% identical), rabbit C2orf80 (63% identical).
Diseases named in the same sentence as C2orf80 in open-access papers:
C2orf80 is named in the same sentence as 3 diseases in open-access papers, as found by Europe PMC text mining. Sharing a sentence is not in itself a finding about the gene and the disease. The quoted sentences say what the papers report.
glioma (2 papers, 2019 to 2021). A benign or malignant brain and spinal cord tumor that arises from glial cells (astrocytes, oligodendrocytes, ependymal cells). "Third, variants in CCDC26 (the 8q24 locus), C2orf80 (close to IDH), LRIG1, PHLDB1, ETFA, MAML2 and ZBTB16 were associated with IDH-mutant glioma." (PMID 31842352, 2019). "Within 2q33.3, which is also a locus associated with IDH1-mutated glioma, the target gene C2orf80 is 50 kb telomeric to IDH1, but whether or how C2orf80 interacts with IDH1 remains to be elucidated." (PMID 33936159, 2021).
psychosis (1 paper, 2015). "In one of these, C2ORF80 along with STMN3A, a gene involved in neurite outgrowth, were the most significantly affected after knockdown of a psychosis susceptibility gene in human neural progenitor cells." (PMID 25681390, 2015).
C2orf80 also shares sentences with these, for which no sentence is quoted: breast carcinoma (1 paper).